PTPN23 (protein tyrosine phosphatase non-receptor type 23)
Diseases named in the same sentence as PTPN23 in open-access papers:
PTPN23 is named in the same sentence as 49 diseases in open-access papers, as found by Europe PMC text mining. Sharing a sentence is not in itself a finding about the gene and the disease. The quoted sentences say what the papers report.
breast carcinoma (6 papers, 2021 to 2025). "In breast cancer, for instance, low expression of PTPN23 is significantly correlated with poor prognosis in patients." (PMID 40570022, 2025). "Protein tyrosine phosphatase N23 (PTPN23) is a key player in breast epithelial cells and an inhibitor of cell motility and invasion in breast cancer cells." (PMID 36740671, 2023). "PTPN23 is identified as a suppressor of cell motility and invasion in breast cancer cells by inhibiting FYN kinase." (PMID 35957898, 2022). "Another notable gene, Protein Tyrosine Phosphatase N23, PTPN23 whose downregulation is correlated with poor survival in breast cancer, was observed to be upregulated in GA-T0 treated GBM cell lines." (PMID 34359676, 2021). "PTPN23 participates in physiological and biochemical processes including inhibition of the pathogenesis of breast cancer and hepatocellular carcinoma (HCC) where PTPN23 inhibits endothelial cell migration through dephosphorylation of focal adhesion kinase (FAK) and interaction with Src kinases." (PMID 36106167, 2022). "The overexpression of FYN in breast cancer has been documented, and thus the proliferative phenotype of breast cancer disappears upon inhibition of FYN expression, suggesting that FYN is a downstream molecule of PTPN23 mediating breast carcinogenesis." (PMID 36740671, 2023). "However, most PTPN family members function as tumor suppressors in breast cancer, including PTPN2, PTPN4, PTPN6, PTPN9, PTPN13, PTPN14, and PTPN23." (PMID 35957898, 2022). "To test whether PTPN23, HCN2, or SGK3 affect Notch levels in breast cancer cells, we first evaluated by Western blot the levels of NOTCH1-3 in a panel of five breast cancer lines of different origin." (PMID 39663000, 2025).
Brain atrophy (3 papers, 2020 to 2021). Partial or complete wasting (loss) of brain tissue that was once present. "While overlapping, a more severe neurological phenotype involving seizures, microcephaly, progressive spasticity, brain atrophy, and hypomyelination of white matter appears to be associated with PTPN23 missense variants located within the BRO1-like, tyrosine–protein phosphatase, and ALIX domains." (PMID 34064836, 2021). "PTPN23 mutations were recently linked to developmental epileptic encephalopathy with hypomyelination, brain atrophy and developmental delay, indicating that functional PTPN23 is also essential for the development of the human nervous system." (PMID 32079660, 2020).
developmental and epileptic encephalopathy (3 papers, 2020 to 2024). An epilepsy associated with developmental impairment that may be due to either the underlying etiology or the superimposed epileptic activity, or both. "Within the cohort of patients experiencing developmental and epileptic encephalopathy (DEE), WES has revealed genetic variants in novel genes (FGF12, GABBR1, GABBR2, ITPA, KAT6A, PTPN23, RHOBTB2, SATB2) and candidate epilepsy-associated genes (CAMTA1, FAT3, GABRA6, HUWE1, PTCHD1)." (PMID 39523358, 2024).
epilepsy (3 papers, 2021 to 2024). A brain disorder characterized by episodes of abnormally increased neuronal discharge resulting in transient episodes of sensory or motor neurological dysfunction, or psychic dysfunction. "Regarding the phenotypic consequences, compelling cases for PTPN23 association with neurodevelopmental disorders and epilepsy have been documented." (PMID 36755664, 2022). "Also in one pediatric epilepsy patient, using whole exome sequencing, a PTPN23 mutation was found supporting its candidacy as epilepsy-associated gene." (PMID 36755664, 2022).
colorectal cancer (2 papers, 2008 to 2025). A primary or metastatic malignant neoplasm that affects the colon or rectum. "In colorectal cancer (CRC), the loss of PTPN23 leads to decreased expression of E-cadherin, along with upregulation of epithelial-mesenchymal transition (EMT) markers such as Vimentin and SNAIL, promoting cell migration." (PMID 40570022, 2025). "Our results provide evidence for frameshift mutations in six of these PTP genes (PTPN21, PTPRS, PTPN5, PTPN23, PTPRA, PTPRE) affecting about 32% of MSI-H colorectal cancers." (PMID 19000305, 2008).
hepatocellular carcinoma (2 papers, 2022). A malignant tumor that arises from hepatocytes. "For instance, the binding of SND1 to the 3′UTR of PTPN23 (protein tyrosine phosphatase nonreceptor type 23) mRNA in human hepatocellular carcinoma (HCC) promotes its RNA degradation." (PMID 36557606, 2022).
hereditary spastic paraplegia (2 papers, 2021 to 2022). Hereditary spastic paraplegias (HSP) comprise a genetically and clinically heterogeneous group of neurodegenerative disorders characterized by progressive spasticity and hyperreflexia of the lower limbs. "Here, we present our clinical and genetic findings of a complex form of hereditary spastic paraplegia associated with biallelic PTPN23 variants in an extended Palestinian kinship of eight affected individuals, six of whom were available for investigation." (PMID 34064836, 2021). "A recent report on hereditary spastic paraplegia (HSPs), for example, revealed that some of these PTPN23 alterations are likely benign and that biallelic alterations in the gene underly the heterogeneity of the complex HSP clinical spectrum." (PMID 36755664, 2022).
Intellectual disability (2 papers, 2020 to 2023). "Notably, patients with bi-allelic variants in NHS and PTPN23 share phenotypes, including developmental brain disorders, intellectual disability, cataracts, and autism." (PMID 36979085, 2023).
microcephaly (2 papers, 2020 to 2021). A congenital or acquired developmental disorder in which the circumference of the head is smaller than normal for the person's age and sex. "Taken together, our findings define pathogenic biallelic PTPN23 variants as a cause of a variable clinical spectrum of neurological disease comprising of complex HSP associated with microcephaly, which may occur without intellectual impairment, or involve more severe neurological disease." (PMID 34064836, 2021).
optic atrophy (2 papers, 2020 to 2022). A disorder characterized by loss of optic nerve fibers. "The causative variants in PTPN23, TMEM126A, NBAS, and WFS1 genes were identified in 4 probands with a recessive form of optic atrophy." (PMID 36071901, 2022). "The clinical information of SOPH syndrome and PTPN23 optic atrophy were described in our previous study." (PMID 36071901, 2022). "Among the cases of recessive optic atrophy, there was one case of short stature, optic nerve atrophy, Pelger-Huet anomaly (SOPH syndrome) caused by NBAS variants, one case of PTPN23 optic atrophy syndrome, one case of TMEM126A optic atrophy, and one case of Wolfram syndrome." (PMID 36071901, 2022). "Second, our panel also did not include the PTPN23 gene, which was recently reported to be involved in hereditary optic atrophy." (PMID 36071901, 2022).
breast tumors (1 paper, 2023). "Hyperphosphorylation of autophosphorylation site tyrosine in FYN was detected in protein tyrosine phosphatase N23 (PTPN23)-deficient breast cancer tumors, confirming that FYN could be a therapeutic target for PTPN23 heterozygous or pure deletion breast tumors." (PMID 36740671, 2023).
cervical tumors (1 paper, 2009). "The HD-PTP protein has been described as a tumor suppressor candidate since it is encoded by the PTPN23 gene, located on the 3p21.3 tumor suppressor gene cluster frequently deleted in human kidney, lung, breast and cervical tumors." (PMID 19340315, 2009).
intellectual impairment (1 paper, 2021). "Given that intellectual impairment may be absent in this clinically variable condition, it is important that PTPN23 be considered for inclusion on spastic paraplegia gene testing-diagnostic panels internationally." (PMID 34064836, 2021).
kidney chromophobe (1 paper, 2025). "Additionally, we performed univariable analysis on 33 cancer types and found that PTPN23 significantly impacts overall survival (OS) in several cancers, including kidney chromophobe (KICH), sarcoma (SARC), skin cutaneous melanoma (SKCM), thyroid carcinoma (THCA), and uveal melanoma (UVM)." (PMID 40570022, 2025).
lung carcinoma (1 paper, 2023). "Thus, our data indicate the existence and hyperactivation of WDR4/PTPN23 axis in human lung cancer and the association of this axis with adverse prognosis." (PMID 37821451, 2023). "Clinically, WDR4/PTPN23 axis is hyperactivated in lung cancer and associated with poor prognosis." (PMID 37821451, 2023). "In human lung cancers, WDR4/PTPN23 axis is upregulated in lung cancer and associated with adverse prognosis." (PMID 37821451, 2023). "Clinically, PTPN23 is downregulated in lung cancer and its low expression correlates with WDR4 high expression and poor prognosis." (PMID 37821451, 2023). "Furthermore, downregulation of PTPN23 protein is frequently observed in various human cancers, including lung cancer." (PMID 37821451, 2023). "Next, we investigated the clinical relevance of WDR4/PTPN23 axis in lung cancer." (PMID 37821451, 2023). "Multivariate Cox regression analysis revealed that higher WDR4 expression and lower PTPN23 expression were independent poor prognostic factors in lung cancer, irrespective of other poor prognostic factor, such as the N stage." (PMID 37821451, 2023).
neurotoxicity (1 paper, 2022). Toxicity that causes injury to the central or peripheral nervous system or damages its function. "The third module included 3 genes in Neurotoxicity (Itpr1, Trim8, Lrp1), 4 in Blood–brain barrier (Ptpn23, Claudin5, Plectin, Mmp2) and 4 in Cognitive function (Slc8a3, Srf, Nf1, Ncam1)." (PMID 35899365, 2022).
osteosarcoma (1 paper, 2025). A usually aggressive malignant bone-forming mesenchymal neoplasm, predominantly affecting adolescents and young adults. "This correlation underscores the significant regulatory role of PTPN23 in the osteosarcoma immune microenvironment and highlights its potential involvement in the functional regulation of macrophages and T cells." (PMID 40570022, 2025). "To investigate the effect of si-PTPN23 on the proliferation of the osteosarcoma cell lines 143B and SJSA-1, we performed CCK8 assays at 24, 48, and 72 hours." (PMID 40570022, 2025). "Based on the findings, the PTPN family, particularly PTPN6 and PTPN23, appears to play a crucial role in the regulation of osteosarcoma." (PMID 40570022, 2025). "Additionally, silencing PTPN23 promotes osteosarcoma cell proliferation by modulating cell cycle proteins, such as PCNA, indicating its mechanistic role in tumorigenesis and its potential as a therapeutic target." (PMID 40570022, 2025).
prostate carcinoma (1 paper, 2021). A carcinoma that arises from epithelial cells of the prostate gland. "Also, activation of PI3K/Akt is observed in prostate cancer disease progression upon the loss of PTP1B, a precedent gene of PTPN23." (PMID 34359676, 2021).
tumor (15 papers, 2008 to 2025). "In our comprehensive analysis, PTPN23 was identified as being linked to the regulation of tumor survival." (PMID 40570022, 2025). "Enrichment analysis linked PTPN23 to interferon signaling and inflammation, emphasizing its involvement in the tumor immune microenvironment." (PMID 40570022, 2025). "To further investigate this finding, we conducted silencing experiments on PTPN23, which revealed its functional role in promoting tumor growth, potentially mediated through the IL-6/JAK/STAT3 signaling pathway." (PMID 40570022, 2025). "This multifaceted approach will help us understand the role of PTPN23 in tumor dynamics and immune interactions in greater detail." (PMID 40570022, 2025). "Currently, the use of SND1 inhibitors (such as pdTp) or miR-142-3p antagonists has been identified as a strategy to upregulate PTPN23, thus inhibiting tumor growth." (PMID 40570022, 2025). "Our research suggests that the PTPN family, particularly PTPN23, plays a crucial role in tumor immune evasion." (PMID 40570022, 2025). "In future studies, we aim to conduct small animal experiments to investigate the effects of PTPN23 inhibition and overexpression on tumor growth, metastasis, and immune responses." (PMID 40570022, 2025). "This intricate balance underscores the importance of PTPN23 as a therapeutic target and its potential implications for enhancing anti-tumor immunity." (PMID 40570022, 2025). "Mechanistically, the tumor-promoting WDR4 acts as an E3 ligase substrate adaptor to trigger PTPN23 proteasomal degradation, which diverts the fate of MVBs towards exosome secretion." (PMID 40908470, 2025). "Our pan-cancer analysis indicated that low PTPN23 expression correlates with poor prognosis across various tumors, suggesting it role as a tumor suppressor, particularly in KICH, SARC, SKCM, THCA, and UVM." (PMID 40570022, 2025). "PTPN23, which features a tumor suppressor function in testicular germ cell tumors, is regulated by miR-142-3p." (PMID 35957898, 2022). "Furthermore, we plan to integrate single-cell RNA sequencing technology to comprehensively analyze the changes in the tumor microenvironment following both PTPN23 inhibition and overexpression." (PMID 40570022, 2025). "Notably, a PTPN23-derived short peptide that blocks the interaction between WDR4 and PTPN23 enables PTPN23 stabilization to promote MVB degradation in tumor cells, thereby reducing exosome secretion." (PMID 40908470, 2025). "Moreover, PTPN23 knockout mice display accelerated tumor growth and lung metastasis in transplantation models." (PMID 40570022, 2025). "Inhibiting PTPN23 may lead to the dysregulation of downstream signaling pathways, potentially increasing the proliferation and survival of tumor cells while simultaneously weakening immune effector responses." (PMID 40570022, 2025). "In contrast, PTPN23 expression was lower in tumors than in adjacent non-tumor tissues." (PMID 37821451, 2023). "In addition, PTPN23 has been nominated as a tumor suppressor candidate gene due to its apparent function in regulating cell migration and possibly autophagy." (PMID 31395947, 2020). "We further observed a negative correlation between WDR4 expression and PTPN23 expression in tumor tissues." (PMID 37821451, 2023). "Besides EGFR, PTPN23 promotes MVB sorting and lysosomal degradation of other oncogenic receptors, such as PDGFR and integrins, and elicits tumor suppressive activities by regulating cell adhesion, migration, and invasion." (PMID 37821451, 2023).
cancer (14 papers, 2009 to 2025). A tumor composed of atypical neoplastic, often pleomorphic cells that invade other tissues. "To validate these findings, we combined GTEx and TCGA datasets, which affirming significant differential expression of PTPN23 across multiple cancer types." (PMID 40570022, 2025). "Our analysis revealed that PTPN23 is generally under-expressed across different tissues and cancer types." (PMID 40570022, 2025). "We conducted a pan-cancer analysis to examine the role of PTPN23 in various malignant tumors using the TCGA pan-cancer database." (PMID 40570022, 2025). "The region of the chromosome that contains PTPN23 gene is frequently deleted in cancers." (PMID 36722216, 2023). "We thus evaluated the influence of WDR4/PTPN23 axis on various cancer hallmarks." (PMID 37821451, 2023). "We also found that PTPN23 showed the most widespread CNV alterations across cancer types." (PMID 36341348, 2022). "However, the mechanism that regulates PTPN23 expression in cancer has not been fully understood." (PMID 37821451, 2023). "The CNV percentage in pan-cancer indicated that heterozygous amplification in cancers were widely found in genes PTPN1, PTPN7, PTPN12 and PTPN14 in most cancers, while heterozygous deletions were widely found in genes PTPN13, PTPN20, PTPN22 and PTPN23." (PMID 37884566, 2023). "In contrast to PTPN23, the dysregulation of PTPRN was not significant with CNVs across cancer types." (PMID 36341348, 2022).
neurodevelopmental disorder (3 papers, 2022 to 2023). A behavioral and cognitive disorder with onset during the developmental period that involves impaired or aberrant development of intellectual, motor, or social functions. "Variants in PTPN23 are associated with an autosomal recessive neurodevelopmental disorder and structural brain anomalies with or without seizures and spasticity (MIM #618890)." (PMID 36978159, 2023). "Biallelic mutations in PTPN23 cause a neurodevelopmental disorder and structural brain anomalies with or without seizures and spasticity (NEDBASS) (OMIM# 618890)." (PMID 37240244, 2023).
genetic diseases (2 papers, 2017 to 2020). "WES enabled timely diagnosing of genetic diseases, validation of causality of specific genetic disorders of PTPN23, KCTD3, SCN3A, PPOX, FRMPD4, and SCN1B, and setting dual diagnoses by detecting two causative variants in distinct genes in the same patient." (PMID 27848944, 2017). "While four patients had previously been identified and reported in the literature, the work presented here details the genetic and phenotypic analyses of the largest series of patients with biallelic disease causing variants in PTPN23, enabling characterization of this novel genetic disorder." (PMID 31395947, 2020).
PTPN23 also shares sentences with these, for which no sentence is quoted: Neurodevelopmental delay (3 papers); developmental delay (2); autism (1); cardiomyopathy (1); cataract (1); colon adenocarcinoma (1); esophageal adenocarcinoma (1); gastric cancer (1); glioma (1); kidney tumor (1); language disorder (1); leukemia (1); movement disorder (1); neurological disease (1); Pelger-Huet anomaly (1); rectum adenocarcinoma (1); renal carcinoma (1); sarcoma (1); skin cutaneous melanoma (1); SOPH syndrome (1); Spastic paraplegia (1); Spasticity (1); stomach adenocarcinoma (1); thyroid carcinoma (1); uveal melanoma (1); Ventriculomegaly (1); Wolfram syndrome (1).